FGF21 (fibroblast growth factor 21)
Diseases named in the same sentence as FGF21 in open-access papers (continued):
Sharing a sentence is not in itself a finding about the gene and the disease.
Obesity (continued). "Investigating the effect of BAT to mediate FGF21 in response to exercise in the presence of obesity could potentially reveal new roles for BAT to mediate FGF21." (PMID 40522819, 2025). "FGF21 is increased in patients with obesity, which is detrimental to cardiovascular health." (PMID 40998786, 2025). "Recent studies have identified several factors released from BAT in response to exercise; here we will discuss 2 of these batokines, including 12,13-dihydroxy-9Z-octadecenoic acid (12,13-diHOME) and fibroblast growth factor 21 (FGF21) in the context of exercise and obesity." (PMID 40522819, 2025). "Additionally, skeletal muscle secretion of Fibroblast Growth Factor 21 (FGF21) is increased, which mediates metabolic adaptations including resistance to diet-induced obesity (DIO) and glucose intolerance in these mice." (PMID 39381436, 2024). "Moreover, FGF-21 is garnering attention as a potential therapeutic target for obesity-related metabolic disorders, including NAFLD, owing to its significant effects on lipid and carbohydrate metabolism." (PMID 39617908, 2024). "However, it is interesting that the expression of FGF-21 in the liver and skeletal muscles of obesity-resistant mice is further elevated compared to obese mice, and the increase in FGF-21 is beneficial for reducing ectopic lipid deposition." (PMID 38732501, 2024). "The complex of these metabolic activities confirms the pleiotropic activity of FGF21, improving insulin sensitivity, hepatic steatosis, and body weight and leading to its recognition as a potential therapeutic target for obesity-related metabolic disorders, including NAFLD/MASLD." (PMID 39409124, 2024). "Elevating FGF21 levels in mice effectively suppresses diet-induced obesity and hyperglycemia." (PMID 39683422, 2024). "Additional work could be carried out to clarify its role in weight gain and obesity development and the impact of weight cycling on FGF21 kinetics." (PMID 38474774, 2024). "Furthermore, FGF21 analogues have been studied both in animal and human models as therapeutics for obesity, T2D, hyperlipidemia, and nonalcoholic steatohepatitis." (PMID 38957656, 2024). "Fibroblast growth factor-21 (FGF-21) and Visfatin are associated with obesity." (PMID 38216702, 2024). "In addition, FGF21 can modulate obesity and hepatic metabolic homeostasis via increased energy consumption and insulin sensitivity." (PMID 38891828, 2024). "FGF21 secretion may act in a paracrine manner to promote thermogenic gene expression in brown adipocytes, thus alleviating diet-induced obesity." (PMID 38957396, 2024). "With the functions of FGF21 in the central nervous system and peripheral tissues, FGF21 may alleviate metabolic disorders such as obesity and diabetes." (PMID 38257122, 2024). "It has been hypothesized that obesity and insulin resistance may lead to a phenomenon similar to insulin or leptin resistance, known as FGF21 resistance, which is considered a self-protective mechanism of the body." (PMID 39409124, 2024). "In this study, FGF21 levels were analyzed in males with obesity after undergoing GS." (PMID 39100807, 2024). "A randomized, placebo-controlled, double-blind proof-of-concept trial conducted in patients with obesity and T2DM revealed that LY2405319 (LY), an investigational FGF21 variant deemed suitable for early-phase clinical development, demonstrated significant improvements in dyslipidemia." (PMID 38312833, 2024). "Circulating levels of FGF21 are increased in subjects with obesity, dyslipidemia, metabolic syndrome, diabetes mellitus, nonalcoholic fatty liver disease, coronary artery disease, atherosclerosis, acute myocardial infarction, diabetic nephropathy, and arterial hypertension." (PMID 39452947, 2024).
Obesity (continued). "However, the clinical implementation of FGF21-based therapies for the treatment of obesity is restricted by the complexity of pathophysiology of FGF21, the potential development of FGF21 resistance in obesity and the poor pharmacokinetic of native FGF2120–24." (PMID 38310105, 2024). "They produced FGF21 KO mice that displayed glucose intolerance and obesity." (PMID 38534427, 2024). "This condition could explain why mice with severe hepatic insulin resistance, due to the absence of hepatic insulin receptor substrates (IRSs) IRS1 and IRS2, exhibit reduced obesity and lower circulating levels of FGF21." (PMID 39409124, 2024). "This discrepancy may be attributed to FGF21 resistance and implies that the dysfunctional FGF21–adiponectin axis contributes to the pathogenesis of obesity-related metabolic syndrome." (PMID 39408777, 2024). "Moreover, these three bacterial strains were significantly associated with certain adipo-myokines related to obesity or inflammation (LIF, FSTL1, FGF21, SPARC, and IL6)." (PMID 39391493, 2024). "The purpose of this study was to evaluate the difference between the levels of NRG4, FGF21, and irisin secreted from brown adipose tissue between metabolically healthy and unhealthy individuals with obesity with equal amounts and distribution of adipose tissue." (PMID 39008201, 2024). "However, increased concentrations of FGF21 are paradoxically observed in heightened insulin resistance, obesity, diabetes, and metabolic syndrome." (PMID 39687000, 2024). "Thus, further investigations are needed to elucidate the molecular mechanisms of FGF21 on bone, particularly as FGF21 analogues/mimetics for the treatment of obesity-related metabolic complications are in various phases of clinical trials." (PMID 39341924, 2024). "Circulating levels of FGF21 are elevated in obesity and NAFLD." (PMID 38238320, 2024). "Together, these results suggest that 11-10-8 LNP-based FGF21 mRNA therapy could be a promising approach for treating obesity and fatty liver." (PMID 38409275, 2024). "Finally, a significant negative association was observed between PM2.5 concentrations and levels of the novel obesity-related biomarker fibroblast growth factor 21 (FGF-21) (OR: 0.148; 95% CI: 0.025-0.89; P FDR = 0.037)." (PMID 38947357, 2024). "Although the role of FGF21 in obesity, diabetes, and non-alcoholic fatty liver disease (NAFLD) in humans and animals has been extensively studied, the hormone's short circulating half-life (30–120 min) and its tendency to aggregate in vitro limit its clinical application." (PMID 39144082, 2024). "Interestingly, two entirely different stimuli, overfeeding and obesity both enhance FGF21 production, predominantly in the pancreas and white adipose tissue probably affecting its liver secretion to a lesser extent." (PMID 39302236, 2024). "It was uncovered that the reversal of obesity-induced FGF21 resistance in adipose tissue could serve as an alternative approach for treating obesity and related diseases." (PMID 38409604, 2024). "As we noticed, most of the anti-obesity gene therapy approaches exploit the possibility of inducing white-to-beige adipose transition by overexpressing the genes coding for secreted factors, such as leptin, FGF21, or BMP7." (PMID 38931457, 2024). "As with irisin and NRG4, FGF21 levels were higher in individuals with obesity suggesting that this increase could be a compensatory response or a result of resistance to FGF21." (PMID 39008201, 2024). "Moreover, there is evidence suggesting that obesity can induce resistance to FGF21, and obese mice exhibit reduced Klotho beta expression." (PMID 38245790, 2024). "FGF21 is a promising intervention therapy for metabolic diseases such as fatty liver, obesity, and diabetes, which is an inducible hepatokine that may be used as a biomarker for normal hepatocyte function." (PMID 39391493, 2024).
Obesity (continued). "It has been hypothesized that the age-related increases in FGF21 are related to the appearance of an FGF21-resistant state, as has been proposed to occur in metabolic diseases such as obesity and type 2 diabetes." (PMID 37914970, 2024). "Also, the investigation of FGF21 levels in HT patients with known obesity, metabolic syndrome, cardiovascular disease, and obesity is necessary to clarify the effect of lower FGF21 on the incidence of the mentioned pathologies." (PMID 39452947, 2024). "Treatment with FGF21 ameliorates metabolic disorders such as insulin resistance, dyslipidemia and obesity in mice, and treatment of human volunteers with FGF21 analogs has shown beneficial effects on metabolic disorders ranging from obesity and type 2 diabetes to non-alcoholic liver diseases." (PMID 37914970, 2024). "FGF-21 increased in the liver and skeletal muscle of obesity-resistant mice." (PMID 38732501, 2024). "However, under the condition of obesity-induced metabolic disturbance, circulating FGF21 levels increase while adiponectin levels decrease in both animals and humans." (PMID 39408777, 2024). "Although functional studies indicate that FGF21 counteracts metabolic derangement, increased circulating levels of FGF21 were observed in subjects with obesity and metabolic syndrome prompting the need for more investigations to understand the physiological role of FGF21." (PMID 39100807, 2024). "To determine the metabolic repercussion of FGF21, we next explored what pathways may be leading to the observed resistance to diet induced obesity in PDSS2BKO mice." (PMID 38212382, 2024). "Our metabolic screening also showed that U90926 deficiency does not impact other major plasma biomarkers of obesity, such as fibroblast growth factor 21 (FGF21), leptin, and insulin." (PMID 38171546, 2024). "In the diabetic KKAy mouse model, liraglutide treatment was shown to suppress both obesity and hyperglycemia, associated with increased hepatic FGF21 production." (PMID 36905134, 2023). "Fibroblast Growth Factor-21 (FGF21) is an endocrine hormone that mediates the fat-liver axis, and in humans and animals, FGF21 can ameliorate insulin resistance, non-alcoholic fatty liver disease, and obesity." (PMID 36756310, 2023). "Therefore, there is a need to develop more potent and effective FGF21 analog drugs for treating diabetes and obesity." (PMID 38116563, 2023). "Treatment with FGF-21 resulted in weight loss and restored the decreased expression of Klotho induced by the high-fat diet, indicating the crucial role of FGF-21 in regulating Klotho expression during obesity development." (PMID 37528365, 2023). "Therefore, if fetuin-A targeting is to be pursued to treat obesity or type 2 diabetes, the potentially deleterious effects fetuin-A on bone homeostasis need to be considered, similar to the case for FGF21 therapy." (PMID 36967758, 2023). "Few clinical studies examining the effects of FGF21 on glycemic control and obesity are available." (PMID 38137540, 2023). "Both FGF21 and GDF15 have been shown to modulate energy balance and glucose homeostasis, and their pharmacological administration leads to promising beneficial effects against obesity and associated metabolic diseases in pre-clinical models." (PMID 37818094, 2023). "Clinical studies have shown that serum levels of FGF21 are elevated in obesity and type 2 diabetes." (PMID 37094639, 2023). "Moreover, researchers recently designed a novel FGF21 named LAPS-FGF21 with a longer half-life via conjugation to the Fc fragment of IgG4, which has shown an excellent therapeutic effect on obesity in mice." (PMID 36594101, 2023). "It is thought that elevated serum FGF21 levels in obese people reflect the existence of fatty liver, and FGF21 may be a biomarker of hepatic lipid accumulation in obesity." (PMID 36967758, 2023). "Moreover, the administration of human FGF21 mRNA reduced insulinemia in mice with diet-induced obesity." (PMID 37948566, 2023).
Obesity (continued). "In conclusion, FGF21 analogs must be tested in new clinical trials, as they appear to exhibit great potential for treating signs of Metabolic Syndrome such as high blood insulin, obesity, and especially hypercholesterolemia." (PMID 37948566, 2023). "In mice with SFD-induced obesity, the effects of FGF21 have been studied only in males." (PMID 37469453, 2023). "Current studies on FGF21 mainly focus on glucose and lipid metabolism, obesity and diabetes." (PMID 37424900, 2023). "Besides its potential function as an anti-obesity drug, FGF21 is suggested to play a role in thermoregulation." (PMID 37355753, 2023). "In a mouse model, obesity was proposed to be a FGF21- resistant condition which might explain why its positive association with BMI was reported in the first trimester." (PMID 36520252, 2023). "Until now, it was unknown to what extent theeffect of FGF21 on taste preferences is reproduced in micewith SFD-induced obesity." (PMID 37469453, 2023). "Another hypothesis of the potential role of FGF21 in renal outcomes may be FGF21 resistance, which is similar to insulin resistance in obesity and type 2 diabetes." (PMID 37009852, 2023). "Similarly, acute exercise under normoxic conditions has been shown to selectively increase plasma FGF-21 in lean individuals, but this response was attenuated in individuals with obesity." (PMID 37123278, 2023). "FGF21 has been shown to play a key role in the control of many aspects of energy homeostasis in both preclinical and clinical studies, and it represents an interesting candidate for the treatment of obesity and type 2 diabetes." (PMID 37266540, 2023). "Moreover, the induction of muscle-derived FGF21 as an adaptive adjustment measure distally regulates insulin signaling, muscle fiber development, energy metabolism homeostasis, obesity, and other systemic problems to improve metabolic characterization." (PMID 38069273, 2023). "Notably, the effect of FGF21 on liver steatosis is sex-specific in obese A(y) mice, showing more beneficial effects on males with melanocortin obesity." (PMID 36594101, 2023). "In recent years, FGF21 has gained attention as an important regulator of metabolic processes at the systemic level, with multiple beneficial effects in different pathologies such as diabetes, insulin resistance, and obesity, among others." (PMID 36909316, 2023). "FGF21 improves obesity and insulin resistance by regulating several molecular mechanisms." (PMID 37755259, 2023). "Studies have shown that obesity is associated with a decrease in circulating and adipose tissue expression levels of FGF21 and Irisin as well as their specific receptors, β‐Klotho and FGFR1 for FGF21 and ITGA5 for Irisin, respectively." (PMID 37462619, 2023). "Interestingly, vital molecular markers involved in glucose metabolism and energy regulation such as AMP-activated protein kinase (AMPK) and fibroblast growth factor 21 (FGF21) are similarly upregulated by metformin treatment in preclinical models of obesity." (PMID 36768561, 2023). "The metabolic function of FGF21 was first described in 2005 in a seminal publication that outlined its capacity to increase glucose uptake in adipocytes, and its ability to protect against obesity, hyperglycaemia, and hypertriglyceridemia in mice." (PMID 36028609, 2023). "Interestingly, FGF21 exogenous administration seems to improve obesity, insulin sensitivity, and reverse steatosis." (PMID 37685811, 2023). "Increased Fibroblast Growth Factor-21 (FGF-21) circulating levels have been described in obesity." (PMID 37409233, 2023). "This indicates that obesity-related increases in FGF21 levels may represent a compensatory mechanism for disease-related metabolic challenges and weight-loss-induced reductions might actually reflect improved metabolic health." (PMID 36891140, 2023). "The level of FGF21 is bound up with metabolism, and FGF21 also mediates obesity in PTC patients." (PMID 37345200, 2023).
Obesity (continued). "The results indicated that FGF21 levels are not influenced by weight loss in a healthy obesity population." (PMID 36594101, 2023). "Previous studies have evidenced that 11β-HSD1 acts as the essential regulator of GCs excess to cause central obesity, highlighting that 11β-HSD1 may play a central role in mediating FGF21 LKO on abrogating OVX-induced obesity." (PMID 37834368, 2023). "Independent of lipid and glucose-modulating effects, manipulation of the FGF21 pathway may potentially be therapeutic for feline obesity and more importantly hepatic lipidosis." (PMID 36756310, 2023). "However, future studies are required to elucidate the downstream targets of FGF21, which possesses the potential of therapeutic targets to treat obesity and T2D." (PMID 37755259, 2023). "Furthermore, pharmacological administration of FGF21 or GDF15 ameliorates obesity and related metabolic complications by improving energy and glucose homeostasis." (PMID 37818094, 2023). "As a stimulator of Akt1 signalling, resistance training exercise might improve metabolic disorders related to obesity via FGF21 production, promoting WAT browing because of endocrine effects." (PMID 37153220, 2023). "Furthermore, selenium supplementation dramatically improved plasma levels of IGF-1, FGF-21, adiponectin, and leptin levels, protecting against diet-induced obesity in mice." (PMID 37755259, 2023). "However, “paradoxical” plasma FGF21 elevation in obesity and diabetes suggests a potential FGF21-resistant state." (PMID 36981616, 2023). "However, FGF21 LKO also caused the dissociation between decreased central obesity and the improvement of obesity-related metabolic syndromes, highlighting a complex role for hepatic FGF21 in the metabolic regulation of estrogen-depleted females." (PMID 37834368, 2023). "FGF21 has been considered a suitable biomarker for predicting many obesity-related situations." (PMID 36594101, 2023). "In particular, the ERK1/2 pathway, considered the primary pathway for FGF21 intracellular signalling, is attenuated in diet-induced obesity mice, as evidenced by reduced expression of immediate early genes in liver and adipose tissue as compared to lean control mice." (PMID 36028609, 2023). "High levels of FGF21 in the blood are characteristic of obesity in rats and humans." (PMID 37712012, 2023). "If human studies are successful, FGF21-boosting therapy might provide a new treatment approach for obesity or NASH." (PMID 36648330, 2023). "FGF21 has several beneficial effects on obesity and obesity-related disorders." (PMID 36837889, 2023). "Furthermore, higher FGF21 level was detected in different metabolic disorders, including type 2 diabetes, obesity and liver steatosis, pancreatitis, and primary mitochondrial dysfunction." (PMID 36761216, 2023). "However, in the available clinical literature, FGF21 levels appear to be paradoxically raised in HF, potentially implying a FGF21 resistant state as occurs in obesity." (PMID 36028609, 2023). "Fgf21 deletion blunted the protection of LKO mice from HFD‐induced obesity." (PMID 37088778, 2023). "Decreased circulating levels of GDF-15 and FGF-21 were associated with greater weight loss at 1 year, regardless of the types of anti-obesity modalities." (PMID 37436597, 2023). "Moreover, in cross-sectional studies, it has also been shown that FGF-21 concentration is elevated in patients suffering from obesity, T2DM, metabolic syndrome, and nonalcoholic fatty liver disease." (PMID 37658393, 2023). "Exercise improves the obesity phenotype in part through the effect of FGF21." (PMID 37576954, 2023). "Furthermore, the pharmacological use of FGF-21 analogues has been proposed in the treatment of dyslipidemia, obesity, type 2 diabetes, and NASH." (PMID 37409233, 2023). "FGF21 analogs or FGF21 receptor agonists might represent an alternative treatment for NAFLD, obesity–associated type 2 diabetes, and other aging–associated metabolic diseases." (PMID 37274345, 2023).